MALAT1 (metastasis associated lung adenocarcinoma transcript 1)
Diseases named in the same sentence as MALAT1 in open-access papers (continued):
Sharing a sentence is not in itself a finding about the gene and the disease.
pancreatic cancer (continued). "In pancreatic cancer, increased expression of MALAT-1 promoted cell growth, migration, and invasion." (PMID 34439315, 2021). "A recent study noted highly expressed MALAT1 in pancreatic cancer cells and tissues as well as exosomes derived from serum of pancreatic ductal adenocarcinoma patients." (PMID 34448533, 2021). "A study also showed that MALAT-1 promoted aggressive pancreatic cancer proliferation and metastasis via stimulation of autophagy." (PMID 34439315, 2021). "Compared with adjacent tissue, the expression level of MALAT1 was significantly increased and the expression level of miR-129-5p was significantly decreased in pancreatic cancer tissues." (PMID 34660566, 2021). "MALAT1 promotes stem cell-like phenotypes of pancreatic cancer cells via upregulating the expression of ZEB1 and self-renewal-related factor Sox2." (PMID 34660566, 2021). "MALAT-1 was observed to exhibit a higher level in pancreatic carcinoma and promote cellular growth and metastasis of pancreatic carcinoma cells." (PMID 34858541, 2021). "For example, increased MALAT1 expression leads to sponging of miR-217 in pancreatic cancer cells, increasing oncogenic KRAS expression." (PMID 31717552, 2019). "As MALAT1 acts as a competitive endogenous RNA for miR-23 in gastric and pancreatic cancer, destabilization of H103 would increase miRNA-binding site accessibility, making MALAT1 a better miRNA sponge for miR-23." (PMID 31717552, 2019). "The transcription factors Sp1, Sp3 and Sp4 are overexpressed in pancreatic cancer cells and like MALAT-1, knockdown of Sp1, Sp3 and Sp4 or Sp1/Sp3/Sp4 (combined) results in decreased cell growth, induces apoptosis, and decreases migration." (PMID 29389953, 2018). "In this study, we show that knockdown of MALAT-1 in Panc1 and other pancreatic cancer cell lines decreases cell proliferation, survival and migration." (PMID 29389953, 2018). "N-myc downregulated gene-1 (NDRG1) which exhibits tumor suppressor-like activity in pancreatic cancer is an example of a gene coregulated by MALAT-1/EZHZ." (PMID 29389953, 2018). "It has been reported that downregulation of lncRNA metastasis associated lung adenocarcinoma transcript 1 (MALAT1) and serine/threonine kinase 38 like (STK38L) lead to the accumulation of LATS1 and decrease the level of cellular YAP in pancreatic cancer cells." (PMID 30486435, 2018). "MALAT-1 is highly expressed in pancreatic cancer and pancreatic CSCs, and its expression confers pancreatic cancer cell stem-like characteristics." (PMID 30310855, 2018). "Since Ras activation is observed in most pancreatic tumors, it is unlikely that drugs targeting MALAT-1 alone would be effective." (PMID 29389953, 2018). "In pancreatic cancer, the oncogenic lncRNA MALAT-1 contributes to the expression of the cancer stem cell marker CD133, CD44, CD24, and aldehyde-dehydrogenase." (PMID 29967761, 2018). "A few lncRNAs (HOTAIR, HULC, MALAT1, HOTTIP) have been found to be associated with pancreatic cancer." (PMID 28294968, 2017). "MALAT-1 is upregulated in pancreatic cancer CSCs and knockdown of MALAT-1 decreases the pancreatic CSC fraction." (PMID 28430163, 2017).
pancreatic cancer (continued). "Data mining of the array data pertaining to several pancreatic cancer cell lines showed that MALAT1 was overexpressed in Aspc-1, Panc-1 and BxPC-3 cells." (PMID 28701723, 2017). "Knocking down MALAT1 reduces pancreatic tumour cell growth and proliferation both in vitro and in vivo." (PMID 28701723, 2017). "In most upregulated lncRNAs, Malat1 was shown to promote pancreatic cancer proliferation by stimulating autophagy, indicating its regulation effect on cell proliferation." (PMID 28747214, 2017). "In this study, we found that MALAT1 promotes pancreatic cancer cellular proliferation and metastasis at least in part by inducing MAPK pathway overactivation." (PMID 28701723, 2017). "Taken together, these results indicate that MALAT1 enhances pancreatic cancer cell growth and proliferation and inhibits cell apoptosis." (PMID 28701723, 2017). "To verify the role of MALAT1 in pancreatic tumours, we knocked down MALAT1 in Panc-1 and Aspc-1 cells using two siRNAs (siMALAT1-1 and siMALAT1-2) to avoid off-target effects." (PMID 28701723, 2017). "In this study, there was a positive correlation of EZH2 and MALAT-1 expression in pancreatic cancer tissues." (PMID 26848980, 2016). "Recent evidence increasingly indicates that the lncRNA MALAT1 contributes to tumorigenesis in several types of human cancer, including colorectal, lung and pancreatic cancers." (PMID 26887056, 2016). "MALAT-1 is potential oncogenic lncRNA involved in proliferation, migration, and invasion and promotes undifferentiated phenotype of pancreatic tumour cells." (PMID 27689078, 2016). "We previously showed that the lncRNA MALAT-1 promoted proliferation, invasion, and metastasis in pancreatic cancer." (PMID 26848980, 2016). "Five well-documented lncRNAs: H19, HOTAIR, HOTTIP, MALAT1, PVT1, which are most closely associated with pancreatic cancer from previous studies were selected as putative lncRNA biomarkers." (PMID 27028998, 2016). "In conclusion, our data indicate that EZH2 recruitment by MALAT-1 and subsequent involvement of the complex in the repression of E-cadherin, promotes pancreatic cancer migration and invasion." (PMID 26848980, 2016). "MALAT1 expression was also higher in pancreatic tumor specimens than in matched normal tissues and was upregulated in seven pancreatic cancer cell lines." (PMID 27686732, 2016). "Next, we detected altered expression of CD133, a putative CSCs marker in pancreatic tumors, following MALAT-1 downregulation by flow cytometry." (PMID 25811929, 2015). "We found that EMT-induced pancreatic cancer cells had higher MALAT-1 expression compared to that of control." (PMID 25811929, 2015). "Collectively, we for the first time found the potential effects of MALAT-1 on the stem cell-like phenotypes in pancreatic cancer cells, suggesting a novel role of MALAT-1 in tumor stemness, which remains to be fully elucidated." (PMID 25811929, 2015). "The detailed mechanism of the regulatory network between MALAT-1 and stem cells related signaling pathway in pancreatic cancer requires further investigation." (PMID 25811929, 2015). "The data together suggest that the enhanced stem cell-like phenotypes of MALAT-1 on pancreatic cancer possibly through upregulating the expression of self-renewal related factors Sox2." (PMID 25811929, 2015). "Additionally, role of AhR and MALAT1 can be studied in pancreatic cancer model by inoculation of AhR-overexpressing pancreatic cancer cells." (PMID 37830596, 2023). "Therefore, the main purpose of this paper aims to analyze the relationship between m6A RNA methylation regulators, PD-L1 and MALAT1 in pancreatic cancer." (PMID 36212476, 2022). "Next, we tested whether METTL3 modulation can govern the expression level of lncRNA MALAT1 in pancreatic cancer cells." (PMID 36212476, 2022).
pancreatic cancer (continued). "We also found that METTL3 controlled the expression of MALAT1 in pancreatic cancer cells." (PMID 36212476, 2022). "Moreover, MALAT1 overexpression increased PD-L1 expression level, while reduction of MALAT1 reduced PD-L1 level in pancreatic cancer cells." (PMID 36212476, 2022). "Furthermore, depletion of MALAT1 attenuated the cell viability at 48 h and 72 h in pancreatic cancer cells." (PMID 36212476, 2022). "Lastly, MALAT1 governed the viability of pancreatic cancer cells." (PMID 36212476, 2022). "Altogether, lncRNA MALAT1 regulates viability of pancreatic cancer cells." (PMID 36212476, 2022). "Moreover, MALAT1 enhanced invasion, migration and viability of pancreatic cancer cells via reduction of EMT and cancer stem cells as well as induction of apoptosis and cell cycle arrest." (PMID 36212476, 2022). "Our data showed that MALAT1 can regulate the expression of PD-L1 in pancreatic cancer cells." (PMID 36212476, 2022). "Strikingly, lncRNA MALAT1 increased the expression of PD-L1 in pancreatic cancer cells." (PMID 36212476, 2022). "Therefore, MALAT1 regulates miRNAs, mRNAs, and proteins in stemness and autophagy pathways in pancreatic cancer." (PMID 34439315, 2021). "Clinical studies demonstrated that MALAT1 was correlated with clinical progression and unfavorable prognosis in pancreatic cancer and that patients with higher expression of MALAT1 had a poorer disease free survival compared to patients with low expression of MALAT1." (PMID 34439315, 2021). "A study showed that an elevated level of MALAT-1 decreased sensitivity to gemcitabine in pancreatic cancer cells, suggesting that down-regulation of MALAT-1 could increase the sensitivity of pancreatic cancer cells to gemcitabine." (PMID 34439315, 2021). "MALAT-1 promoted spheroid formation and resistance to gemcitabine in pancreatic cancer cells as well as tumorigenicity in vivo by stimulating the expression of self-renewal-associated stem cell transcription factors and other proteins, including OCT4, NANOG, SOX2, BMI1, β-catenin, and c-Myc." (PMID 33799834, 2021). "In the present study, a miRNA response element for miR-129-5p on MALAT1 sequence was identified in pancreatic cancer cells, and it was revealed that miR-129-5p could be sponged and repressed by MALAT1." (PMID 34660566, 2021). "As mention early, MALAT1 is another oncogenic lncRNA highly expressed in pancreatic cancer." (PMID 34439315, 2021). "In addition, several ncRNAs such as AFAP1-AS1, UCA1, HOTAIR, PVT1, MALAT-1, circ-ADAM9, BC008363, circ-LDLRAD3, circ-IARS, circ-PDE8A, circ_0030235, and circ_0001649 have been associated with prognosis of pancreatic cancer." (PMID 34439315, 2021). "Besides, MALAT1 and miR-129-5p expressions were found to be negatively correlated in pancreatic cancer samples." (PMID 34660566, 2021). "However, high expression of MALAT-1 has been found in various cancer tissues including pancreatic cancer; therefore, MALAT-1 is considered as an oncogenic lncRNA." (PMID 34439315, 2021). "Importantly, overexpression of MALAT-1 has been correlated with advanced tumor stages, metastasis, and poor survival in pancreatic cancers." (PMID 34439315, 2021). "In addition, studies on MALAT1 in pancreatic cancer largely suggest an oncogenic function of this lincRNA." (PMID 32727085, 2020). "MALAT1 RNA is degraded by miR-200c-3p and miR-217 in pancreatic cancer cells." (PMID 32174966, 2020).
pancreatic cancer (continued). "Our finding of a significantly reduced expression of MALAT1 in PDAC is partially contradictory to a previous study that analyzed the clinical significance of MALAT1 in pancreatic cancer using multiple datasets from different public databases (GEO, Oncomine, TCGA)." (PMID 32727085, 2020). "For example, MALAT1 was found to be upregulated in tumours compared to adjacent normal tissue and its downregulation inhibited cell proliferation, migration, invasion, and promoted apoptosis in pancreatic cancer cell lines." (PMID 32727085, 2020). "Metastasis-associated lung adenocarcinoma transcript-1 (MALAT-1) is a long non-coding RNA (lncRNA) that is a negative prognostic factor for patients with pancreatic cancer and several other tumors." (PMID 29389953, 2018). "Thus, results of this study confirm the pro-oncogenic activity of MALAT-1 in pancreatic cancer cells and demonstrate that this activity is distinct from that previously observed for HOTAIR and HOTTIP in Panc1 cells." (PMID 29389953, 2018). "High MALAT1 staining was found in colorectal, breast and pancreatic cancer." (PMID 30189670, 2018). "Recent studies show that MALAT-1 is a negative prognostic factor for pancreatic cancer and results of our studies also demonstrate that MALAT-1 exhibits pro-oncogenic functions in pancreatic cancer cells and the effects are similar to those observed in other tumors." (PMID 29389953, 2018). "We also observed high expression of MALAT-1 in pancreatic cancer cells; knockdown of MALAT-1 (siMALAT-1) in Panc1 and MiaPaCa2 cells decreased cell proliferation and induced G2/M arrest and induced apoptosis as indicated by increased Annexin V staining and expression of cleaved PARP." (PMID 29389953, 2018). "In pancreatic cancer, the lncRNA MALAT-1 is a regulator of EMT." (PMID 29967761, 2018). "However, one study reported that MALAT1 promotes pancreatic cancer proliferation via the stimulation of autophagy." (PMID 29162158, 2017). "The present study was designed to examine MALAT1 expression and function in pancreatic cancer, to determine whether MALAT1 is a target of miR-217 and to elucidate the interaction between MALAT1 and KRAS." (PMID 28701723, 2017). "Knockdown of MALAT-1 increased sensitivity to gemcitabine in pancreatic cancer cells." (PMID 28430163, 2017). "We confirmed that MALAT1 is upregulated in pancreatic tumours and PDAC cell lines." (PMID 28701723, 2017). "MALAT1 is highly expressed in pancreatic cancer and is thought to enhance stem cell-like phenotypes and its expression has been significantly correlated with the malignant statues of pancreatic cancer patients." (PMID 28294968, 2017). "MALAT-1 might serve as an oncogenic lncRNA in pancreatic cancer by promoting epithelial-mesenchymal transition and stimulating the expression of self-renewal factors such as Sox2." (PMID 26880946, 2016). "In addition, we found a positive correlation between EZH2 and MALAT-1 expression in pancreatic cancer tissues." (PMID 26848980, 2016). "Notably, lnc-SCYL1-1, often called MALAT1, is a crucial factor for enhancing stem cell-like phenotypes in pancreatic cancer." (PMID 26918340, 2016). "And knockdown of MALAT-1 upregulated E-cadherin mRNA expression in pancreatic cancer cell lines." (PMID 26848980, 2016). "Recent study found that knock-down of MALAT1 expression could inhibit pancreatic cancer cell proliferation, migration, invasion and the process of epithelial-mesenchymal transition, and induce cell apoptosis and G2/M cell cycle arrest in vitro." (PMID 27777857, 2016). "And EMT plays a critical role in MALAT-1 mediated pancreatic cancer migration and invasion." (PMID 25811929, 2015). "We finally examined whether MALAT-1 promoted the growth of pancreatic cancer cells in vivo, as the tumorigenic capacity in vivo is considered to a characteristic feature of CSCs." (PMID 25811929, 2015).
pancreatic cancer (continued). "Our previous study indicated that MALAT-1 may serve as an oncogenic long noncoding RNA in pancreatic cancer by promoting epithelial-mesenchymal transition (EMT) and regulating CSCs markers expression." (PMID 25811929, 2015). "In addition, the nude mouse transplantation tumor experiment displayed that MALAT-1 enhanced the tumorigenicity pancreatic cancer cell in vivo." (PMID 25811929, 2015). "In conclusion, our finding suggests a novel role of MALAT-1 that could enhance stem cell-like phenotypes in pancreatic cancer cells, which remains to be fully elucidated." (PMID 25811929, 2015). "We isolated MALAT1 from our screens of melanoma metastasis- and leukemic blasts-derived cDNA libraries, while Super-SAGE expression analysis of the long non-coding MALAT1 RNA expression profile detected a 4-fold increase in pancreas carcinoma compared with normal tissue." (PMID 23717670, 2013). "Moreover, MALAT-1 knockdown promotes chemosensitivity to Gemcitabine in pancreatic cancer." (PMID 38201661, 2024). "According to studies, MALAT1 may play a role in the malignancy phenotypes of pancreatic cancer." (PMID 39170516, 2024). "Moreover, MALAT1 was involved in efficacy of gemcitabine treatment in pancreatic cancer patients." (PMID 36212476, 2022). "Notably, METTL3 positively regulates the expression of lncRNA MALAT1 in pancreatic cancer cells." (PMID 36212476, 2022). "Besides, MALAT1 negatively modulated miR-129-5p expression in pancreatic cancer cells." (PMID 34660566, 2021). "In addition, we found that MALAT1 knockdown promoted cell apoptosis in pancreatic cancer cells." (PMID 28701723, 2017). "Therefore, we hypothesize that MALAT-1 could enhance stem-like properties in pancreatic cancer cells." (PMID 25811929, 2015). "Therefore, we hypothesize that MALAT-1 could enhance stem-like phenotypes in pancreatic cancer cells." (PMID 25811929, 2015). "In addition, subcutaneous nude mouse xenografts revealed that MALAT-1 could promote tumorigenicity of pancreatic cancer cells in vivo." (PMID 25811929, 2015). "Therefore, we hypothesized that MALAT-1 might enhance stem cell-like phenotypes in pancreatic cancer cells." (PMID 25811929, 2015). "LncRNA MALAT1 acts as a ceRNA of miR-141-5p and elevated expression of MALAT1 promotes EMT of pancreatic cancer cells through the miR-141-5p-TGFβ-TGFβR1/TGTβR2 axis." (PMID 39937018, 2025). "TCDD exposure resulted in a significant increase in MALAT1, EZH2, and H3K27me3 levels but exposure to AhR antagonists exhibited the reversed functions of MALAT1, EZH2, and H3K27me3 in AhR-overexpressing pancreatic cancer cells." (PMID 40765830, 2025). "LncRNA MALAT1 modulated METTL3-mediated PD-L1 expression and affected immune infiltrates in pancreatic cancer." (PMID 38638430, 2024). "MALAT-1 can regulate Kirsten rat sarcoma virus (KRAS) expression by means of competitive inhibition, thereby increasing cell proliferation in pancreatic cancer." (PMID 38559560, 2024). "MALAT-1 knockdown was found to reduce levels of SOX2, suggesting regulation of SOX2 by MALAT-1 contributes to the CSC phenotype in pancreatic cancer." (PMID 28430163, 2017). "Therefore, we investigated whether MALAT1 is a target for miRNAs in pancreatic tumours." (PMID 28701723, 2017). "The results suggest that MALAT1, HOTTIP and PVT1 as predictors to predict the efficacy of GEM based chemotherapy in first-line treatment of pancreatic cancer patients." (PMID 29221115, 2017). "Consistent with our observation that KRAS protein expression levels decreased after MALAT1 knockdown was our observation that MALAT1 knockdown also downregulated the MAPK signalling pathway, which is constitutively activated in pancreatic tumours." (PMID 28701723, 2017).